AFP (alpha fetoprotein)
Diseases named in the same sentence as AFP in open-access papers (continued):
Sharing a sentence is not in itself a finding about the gene and the disease.
tumor (continued). "Age < 40 years, abnormal AST, max tumor size > 5 cm, positive MVI and low differentiated tumor were the main impacts of OS, while age < 40 years, AFP ≥ 400 ng/mL, max tumor size > 5 cm, positive MVI and low differentiated tumor were the major contributing factors of RFS." (PMID 37312215, 2023). "The ability of tumor cells to evade immune surveillance by downregulating MHC class I molecules on its surface and the intracellular localization of AFP provide considerable challenges to AFP-targeting therapies." (PMID 38173713, 2023). "It is hypothesized that the cancerous cells produce alpha-fetoprotein (AFP), which up-regulates the expression of vascular endothelial growth factor (VEGF) proteins, leading to the formation of endovascular tumor embolization." (PMID 37950062, 2023). "Several promising CAR-T cell tumor targets were identified, including Glypican-3 (GPC3), alpha-fetoprotein (AFP), NK group 2 member D ligand (NKG2DL), Mucin 1 glycoprotein 1 (MUC1), Epithelial cell adhesion molecule (EpCAM), Claudin18.2 (CLD18), CD147, CD133, HBV surface protein, and c-MET." (PMID 36980692, 2023). "Of note, the patient who had both graft rejection and tumor recurrence after liver transplantation had high alpha-fetoprotein levels pretransplant and had not received targeted therapy, indicating a higher tumor burden." (PMID 37958291, 2023). "Moreover, an inverse correlation between the T-cell–inflamed tumor microenvironment (TME) and AFP levels, especially in seminoma cases, was reported." (PMID 38069192, 2023). "Additionally, AFP and PIVKA-II models display excellent performance in distinguishing resected tumor HCC, comparable to the observation of Li Y." (PMID 37932802, 2023). "In this study, we have adopted the primitive diagnosis criteria—the area of hepatocellular differentiation was found in the tumor tissue, no matter the level of AFP value—as the selection standard." (PMID 36647059, 2023). "Serum AFP levels are not always related to tumor burden which is characterized by an atypical fluctuation within its reference range in advanced HCC before proper clinical treatments." (PMID 37781207, 2023). "In laboratory results, there were no abnormal levels, other than elevation of the serum tumor markers alpha-fetoprotein (AFP) at 619 ng/ml and neuron-specific enolase (NSE) at 69.4 ng/ml." (PMID 37721573, 2023). "Serum PIVKA-II level may reflect extrahepatic disease progression after LT better than AFP level, because PIVKA-II can induce tumour cell proliferation and promote tumour angiogenesis." (PMID 37024609, 2023). "However, the distributions of other clinicopathologic factors including age, gender, the number of retrieved LNs, tumor location, BMI and preoperative CEA and AFP levels were comparable between micro-LN-positive and micro-LN-negative patients." (PMID 37308852, 2023). "High TLK2 expression was strongly correlated with male gender (p = 0.028), higher levels of AFP (p = 0.033) and ALBI score (p < 0.001), worse MVI (p < 0.001), larger tumor diameter (p < 0.001), greater tumor number (p = 0.008) and more advanced TNM stage (p < 0.001)." (PMID 38343446, 2023). "However, the levels correlated strongly with cancer stage, and statistically significant differences in relation to tumor size, portal vein tumor thrombus (PVTT), extrahepatic metastasis (EHM), AFP, and BCLC staging were observed." (PMID 40357132, 2023). "The ECOG PS score, Child-Pugh classification, ALBI grade, extrahepatic metastasis, tumor number, largest tumor size, and AFP level were not significantly correlated with OS and PFS." (PMID 37916160, 2023). "In conclusion, HBP radiomic features were closely associated with GPC3-positive expression, and the combination of age, AFP >400 ng/mL, and non-smooth tumor margin provided an effective way to non-invasively and individually predict GPC3-positive HCC patients." (PMID 37841420, 2023).
tumor (continued). "Fucoidan alone did not significantly decrease the expression of AFP (alpha fetoprotein), a key marker of tumor burden and prognosis, VEGF or VEGFR, although a reduction in their levels was observed in combination with the anti-angiogenic drugs." (PMID 37233501, 2023). "In the training cohort, age, serum AFP >400 ng/mL, and non-smooth tumor margin were incorporated, and the top 11 features were combined to construct the nomogram." (PMID 37841420, 2023). "Given the elevated AFP and potential burnt-out yolk sac tumor component, this tumor was determined to be a nonseminoma and was therefore treated as a nonseminoma with the following staging characteristics: pT1bNxM0, stage IS." (PMID 37485120, 2023). "Considering only the presence of tumor or total tumor diameter, rather than this grouping, only AFP had significance in all statistical analysis." (PMID 37910585, 2023). "After the tenth course, the serum levels of AFP and DCP were within the normal range, the intrahepatic HCC had shrunk to 73 mm with regression of the right hepatic hilum tumor contact, and the patient was diagnosed with a partial response to the modified RECIST." (PMID 37266831, 2023). "Our findings also suggested that age, tumor number, MVI, preoperative AFP level, preoperative CA19-9 level, and ECOG PS score are significantly associated with recurrence in HCC patients who undergo conversion hepatectomy and were previously treated with transarterial interventional therapy." (PMID 37689775, 2023). "Following the hepatectomy, their serum AFP levels have consistently remained within normal limits, and CT imaging has indicated the absence of tumor recurrence over a span of 36 months." (PMID 37686291, 2023). "Again, this is a mixed predictive model, combining radiomics data with clinical data: presence or absence of cirrhosis, radiological data: regular or irregular tumor margins, and biological data: ALBI score and AFP level, to obtain a better predictive power, with a time-dependent AUC of 0.803." (PMID 37046521, 2023). "The imaging method to measure tumor size was not mentioned in that study, and the diagnosis was based on either biopsy or a serum alpha-fetoprotein > 300 ng/mL." (PMID 38137868, 2023). "In this analysis, pT-category and pre-transplant AFP-level were independent statistically significant factors for 10 year cumulative recurrence rates but tumor to liver SUV ratio was not." (PMID 35451699, 2023). "The patient had a surgical age of 9 months, a preoperative AFP of 77.0 ng/ml, a tumor size of approximately 4.9 cm, and no normal testicular tissue during the operation." (PMID 36795187, 2023). "Although the serum tumour markers total beta-HCG and AFP are widely used, they lack specificity, and their diagnostic ability may depend on several factors, including the type of assay used and the upper reference level of the determination." (PMID 38067334, 2023). "Serum AFP was increased (43.24–90,474 ng/mL) in 17 patients, and a normal level (3.8 ng/mL) was found in one patient, whose primary tumor was located in the mediastina." (PMID 38125762, 2023). "Furthermore, NLR was statistically significantly higher in TC patients with normal serum tumor markers (BHCG, AFP, LDH) compared with the control group." (PMID 36983756, 2023). "Another significant result from our preclinical study is that AFP immunization has no efficacy against already-formed c-MYC/Mcl1 tumor lesions due partly to immune escape from AFP-specific T cells." (PMID 37040183, 2023). "AFP and DCP have been reported to reflect not only tumor burden, but also TME." (PMID 37686624, 2023). "AFP has become the most widely used clinical biomarker for the diagnosis and prognosis of HCC, and high AFP levels have been shown to correlate with HCC progression, postoperative tumor recurrence, and metastasis." (PMID 37841420, 2023). "The final model (FAIL-T) included AFP, AST, tumor sIze, ALT, and Tumor number." (PMID 37200967, 2023).
tumor (continued). "Regardless of the tumor size (<5 or ≥5 cm), AFP level (<400 or ≥400 ng/mL), and BCLC stages (0–A, B, C–D), the 3-year OS rate of Huaier users was significantly higher than that of non-Huaier users." (PMID 37251326, 2023). "Only around half of HB cases show elevated AFP levels above the upper reference values, as tumor-derived AFP levels are often not significantly higher than the physiologically high levels observed during the first months of life." (PMID 37686577, 2023). "Furthermore, We investigated marker capacity for those undergoing tumor resection and noted an extremely high performance of PIVKA-II (AUC = 0.930), AFP + PIVKA-II (AUC = 0.936), and AFP + PIVKA-II + AST models (AUC = 0.966, P = 0.044)." (PMID 37932802, 2023). "In terms of diagnosis and recurrence monitoring, miRNA demonstrates higher specificity (93.4%) and sensitivity (88.7%) compared to AFP, regardless of the histopathological type, patient age, or anatomical location of the tumor." (PMID 37686577, 2023). "Besides, KLF14 expression was significantly correlated with tumor size, TNM stage, serum AFP level and portal vein tumor thrombus (PVTT) in patients with HCC." (PMID 36600258, 2023). "Thereafter, the AFP level gradually increased, reaching a maximum of 34.9 ng/mL at the 33rd week, and there was no radiological evidence of tumor collapse." (PMID 38115376, 2023). "However, admission laboratory investigations were entirely normal, including tumor markers, such as eta-human chorionic gonadotropin (β-HCG) and alpha fetoprotein (AFP)." (PMID 37189109, 2023). "Compared with the other scoring systems based on tumor size and tumor number, the ALBI-TAE model, which consists of up-to-11 criteria, ALBI grade, and serum AFP level, offered a significantly higher C-index (0.633) than the SEC (0.578), SAT score (0.574), and tumor burden score (0.546)." (PMID 37248526, 2023). "On immunohistochemical staining of the tumor, Hep Par-1 and Glypican 3 were negative, but alpha-fetoprotein was positive." (PMID 38156130, 2023). "Previously, we demonstrated that AFP is not merely a tumor marker but also reflects the malignant nature of HCC with stem cell features." (PMID 35955438, 2022). "Our hypothesis of re‐differentiation/aberrant differentiation is also supported by clinical phenomena involving tumor biomarkers, such as cancer antigen 125 (CA125) and AFP." (PMID 35285179, 2022). "Recently, dendritic SiNP have been utilized to potentiate the diagnostic value of CA125, cancer embryonic antigen (CEA), and alpha-fetoprotein (AFP) by providing a multiplexed barcode sensor that allows for sensitive and high throughput assays of tumor markers versus standard immunochemistry." (PMID 36077371, 2022). "An AFP L-3 < 35% and PIVKAII < 400 mAU/ml allows safe expansion on tumor size and number while HCC exceeding these cutoff might yield unacceptable results even in patients fulfilling traditional criteria." (PMID 34117916, 2022). "The tumor markers [alpha-fetoprotein, beta-hCG, and lactate dehydrogenase (LDH)] were within normal ranges." (PMID 36550579, 2022). "Good OS was associated with a lower BCLC classification (P < 0.001), no PVTT (P < 0.001), a single tumor (P = 0.029), a lower level of AFP (P < 0.001), and intrahepatic local treatment (P< 0.001)." (PMID 35183265, 2022). "We observed stronger MBD3-positive staining in HCC patients with a higher AFP level, no tumour capsules and poor cell differentiation." (PMID 35501390, 2022). "Numerous studies have reported that clinical characteristics and routine laboratory examinations of blood are prognostic predictors for HCC, including tumor size, HBV DNA, alpha-fetoprotein (AFP), neutrophil/lymphocyte ratio (NLR), and alkaline phosphatase (ALP)." (PMID 36184588, 2022).
tumor (continued). "However, when the pruritus became more severe at the 28th week, a second test revealed a markedly elevated TBA level as high as 143 μmol/L, a mild elevation of alanine aminotransferase (ALT), and abnormal tumour markers CA125 and alpha-fetoprotein (AFP)." (PMID 36324123, 2022). "Fifteen studies with 1112 patients indicated that the effect of HuoxueHuayu therapy in decreasing tumor markers was better than conventional treatment (p < 0.05), typically in the level decline of CEA (7 studies) and AFP (8 studies)." (PMID 38094221, 2022). "AFP is involved in multidrug resistance (MDR) by activating the PI3K/AKT/mTOR signalling pathway, which leads to metabolic reprogramming of cancer stem cells, inhibition of the expression of apoptosis‐related enzymes and resistance to tumour cell apoptosis." (PMID 36181321, 2022). "The immunohistochemical staining of ALP showed higher expression in non-cancerous areas than in the tumor part, but that of AFP showed higher expression in the tumor part." (PMID 35455635, 2022). "Although positively correlated with elevated AFP and poor tumor differentiation, CD4+ tumor infiltrating lymphocytes (TILs) are associated with neither overall survival nor disease-free survival." (PMID 35321670, 2022). "In our study, higher AFP levels, incomplete tumor capsule, non-smooth tumor margins, and higher Edmondson grade were more common in the high Ki-67 expression group, which is consistent with previous studies." (PMID 35875154, 2022). "There were significant differences in 3-Point in AFP, PIVKA-II, ALP, and tumor number." (PMID 35294742, 2022). "Similar to those in the PME-O, patients with RIhigh were more likely to have shorter survival time and higher AFP level and multiple tumors rather than single tumor." (PMID 35314790, 2022). "Utilization of the NYCA score for candidate selection tremendously expands the proportion of patients hitherto deemed non-transplantable due to high static AFP/ tumor burden, without compromise to recurrence-free survival." (PMID 36290870, 2022). "Moreover, HCC patients with high AFP serum levels (> 300 ng/mL) and positive staining for the epithelial cell adhesion molecule EpCAM show significantly higher microvessel density and tissue expression of vascular endothelial growth factor, which may be related to tumor angiogenesis." (PMID 36258212, 2022). "Among gynecologic cancer, AFP was not a reliable tumor marker for screening or diagnosis, so it was usually combined with other markers to achieve better sensitivity and specificity." (PMID 36553184, 2022). "However, it is confirmed that in many tumors, they can be used as biomarkers for tumor diagnosis and prognostic analysis, and the combined diagnosis of CEA or AFP is better." (PMID 36158677, 2022). "Serum markers alpha-fetoprotein (AFP) and carbohydrate antigen 19-9 (CA19-9) were not specific for CHC, even though the combination of imaging features and tumor markers as diagnostic criteria still indicated inadequate diagnostic efficiency." (PMID 35241004, 2022). "In tumor rupture group, seven (77.8%) patients achieved CR at the end of the treatment, and only two showed mildly increased AFP level without residual disease on imaging." (PMID 35391745, 2022). "Since AFP level is related to a higher tumor burden and MiVI rate, the trend and final level of AFP at the end of downstaging procedure further elucidates tumor biology, although there is no consensus concerning the optimal AFP threshold before LT." (PMID 36046928, 2022). "Our analysis revealed that 11 variables were significant predictors for both OS and RFS: large tumor size (> 5 cm), multiple tumor number (≥ 2), incomplete tumor capsule, positive MVI, BCLC-C stage, Edmonson grading III–IV, ALT > 40U/L, AST > 40 U/L, AFP > 400 ng/mL, CA19-9 > 37 U/mL, and TMT (DP)." (PMID 36258212, 2022).
tumor (continued). "In preclinical models, intra-tumoral injection (and to a significantly lesser extent, IV injection) of AFP-CAR-T in NSG mice bearing HLA-A*02:01 HCC SK-HEP-1-MG and HEPG2 tumour cells expressing the AFP158–166 epitope, controlled tumour growth compared to controls." (PMID 35158772, 2022). "Thirty studies with 1961 patients reported the level of tumor markers including CA125 (8 studies), CEA (20 studies), CA153 (2 studies), AFP (11 studies), AFU (1 study), CA199 (14 studies), CYFR21-1 (2 studies), VEGF (2 studies), CA50 (1 study), and CA724 (1 study)." (PMID 38094221, 2022). "We firstly mined the cDNA expression data of the 1,884 human HCC samples, which showed that the SPINK1 gene was significantly overexpressed in stage I–IV tumor samples relative to para-tumor specimens and presented better discrimination and calibration capabilities for HCC detection than AFP." (PMID 35924241, 2022). "EMA is almost always negative and only occasionally, the tumor is positive for AFP and negative for glypican and CD117." (PMID 36140449, 2022). "After PSM, the predictive nomogram included Child-Pugh score (A/B), CNLC (IIa/IIb), ascites (no/yes), AFP (<400/≥ 400 μg/L), tumor size (<5/≥5 cm), anti-HCV (negative/positive), and treatment (TACE/LR)." (PMID 37304009, 2022). "Among them the fucosylated fraction of AFP, proteoglycans such as glypican 3 and versican, DCP and PIVKA II have been principally investigated for early-stage HCC detection, treatment response monitoring and tumor prognosis evaluation." (PMID 36230569, 2022). "Serum AFP, CA19-9, and CEA are used as preoperative tumour markers." (PMID 36345011, 2022). "Univariate analysis of the training cohort revealed that HBV-DNA, HBeAg, AFP level, NEU concentration, LYM concentration, GGT level, tumour diameter, number of tumours, histologic differentiation, MVI, and satellite lesions were significantly associated with RFS." (PMID 36100893, 2022). "The protective role of PDE2A was also observed in high PDE2A expression HCC patients with no vascular invasion, tumor-free status, and low serum AFP levels." (PMID 36611861, 2022). "Blood biochemistry, urinalysis, and tumor marker levels (AFP, HCG, and LDH) showed no abnormal findings." (PMID 36335378, 2022). "Moreover, IL-17 blockade led to a 2-fold decrease in AFP+ and CD133+ cells counted in both peri- and intra-tumor areas." (PMID 35342340, 2022). "In the univariate analysis, positive HBsAg status, poor tumor differentiation, tumor size > 5 cm, presence of MVI, AFP > 400 ng/μL, distant metastasis and high CEBPA-DT expression were identified as potential risk factors associated with dismal OS and RFS of HCC patients." (PMID 36471363, 2022). "In contrast to the FP-based biosensor made of QDs, multicolor QDs have been developed for a FP immunoassay that could detect two tumor markers, carcinoembryonic antigen (CEA) and alpha-fetoprotein (α-AFP), simultaneously in human serum." (PMID 35955779, 2022). "According to this model, the overall 5-year survival rate reached 79.7%, and tumor recurrence could be more accurately estimated than with the Milan, UCSF, AFP model, or Up-to-7 criteria." (PMID 35053580, 2022). "Other clinico-pathological parameters such as age, tumor number, preoperative serum alpha-fetoprotein, vascular invasion, and tumor differentiation were not correlated with TMEM106A methylation." (PMID 35713314, 2022). "The univariate and multivariate analyses revealed that tumor size (HR [95%]: 1.553[1.151–2.095], P = 0.004), periportal HCC (HR [95%]: 2.200[1.111–4.358], P = 0.024) and AFP ≥ 400 (HR [95%]: 2.431[1.000–5.907], P = 0.004) were independent prognostic factors for LTP after RFA." (PMID 34983650, 2022). "Furthermore, patients having an elevated AFP level and vascular invasion had a high expression level of TMCO1-AS1 in tumor tissue." (PMID 35141283, 2022).